LINC01116 (long independently transcribed non-coding RNA 1116)
Synonyms: TALNEC2
Gene: Long non-coding RNA gene on chromosome 2 (176,611,437 to 176,637,931, reverse strand). Ensembl gene ENSG00000163364.
Diseases named in the same sentence as LINC01116 in open-access papers:
LINC01116 is named in the same sentence as 26 diseases in open-access papers, as found by Europe PMC text mining. Sharing a sentence is not in itself a finding about the gene and the disease. The quoted sentences say what the papers report.
glioma (16 papers, 2017 to 2023). A benign or malignant brain and spinal cord tumor that arises from glial cells (astrocytes, oligodendrocytes, ependymal cells). "LINC01116 has been implicated in osteosarcoma, gastric cancer, glioma, and head and neck squamous cell carcinoma, for promoting the proliferation, invasion, and migration of tumor cells." (PMID 34690553, 2021). "LINC01116 regulates diverse cancers, including glioma, HNSCC, breast cancer, osteosarcoma, epithelial ovarian cancer and oral squamous cell carcinoma." (PMID 37340445, 2023). "LINC01116 has been identified as a carcinogenic molecule for a variety of human cancers, including gastric cancer, osteosarcoma, glioma." (PMID 33726770, 2021). "LINC01116 is abnormally upregulated in a variety of tumors and has been found to promote tumor growth in glioma by targeting VEGFA23–25." (PMID 32358484, 2020). "Taken together, these findings unveil a mechanism of TNAs-mediated glioma progression and biological roles of LINC01116 in glioma." (PMID 32358484, 2020). "RNA immunoprecipitation results from a microarray study showed that LINC01116 competed with VEGFA to bind with miR-31-5p in tumorigenesis of glioma." (PMID 32315285, 2020). "To further validate the results of bioinformatics analysis, we used qRT-PCR to detect the expression level of LINC01116 in 27 glioma tissues and 10 normal brain tissues obtained from patients with traumatic brain injury." (PMID 32358484, 2020). "However, knockdown of LINC01116 also inhibited migration of glioma stem cells, while overexpression of LINC01116 promoted invasion and migration of gastric cancer cells." (PMID 34193551, 2021). "In glioma, LINC01116 is overexpressed and can target VEGFA to promote the tumorigenesis of glioma." (PMID 33535997, 2021). "To explore the biological functions of LINC01116 in glioma cells, we examined LINC01116 expression in cell lines, as shown in the figure, which was significantly higher in human glioma cells (Ln229, U87, and U251) than in normal brain astrocyte cell line (SVG)." (PMID 32358484, 2020). "Mechanistically, LINC01116 directly binds to and recruits DDX5 to the IL-1β gene promoter in glioma cells to increase the expression of IL-1β which in turn promotes glioma progression and recruits neutrophil to glioma." (PMID 37596619, 2023). "LINC01116 recruits DDX5 to the IL-1β promoter and activates IL-1β expression to promote neutrophil recruitment and glioma proliferation." (PMID 35992805, 2022). "Besides, existing study reported that overexpression of LINC01116 promotes cell progression including angiogenesis of glioma and in CRC, but more data are required for exploring the mechanism of LINC01116 regulation in CRC." (PMID 33499872, 2021).
osteosarcoma (8 papers, 2017 to 2023). A usually aggressive malignant bone-forming mesenchymal neoplasm, predominantly affecting adolescents and young adults. "Previous studies showed that the expression of LINC01116 is upregulated in Gefitinib resistance non‐small lung cancer, Doxorubicin resistance osteosarcoma, and Cisplatin resistance lung adenocarcinoma cells." (PMID 37321964, 2023). "LINC01116 has been reported to be an oncogene in multiple cancers, including osteosarcoma." (PMID 33762953, 2021). "LINC01116 was overexpressed in various tumors, such as osteosarcoma, nasopharyngeal carcinoma and some others, another study found that LINC01116 was overexpressed in LUAD tissues and cell lines and suggested that LINC01116 may act as an oncogene in LUAD." (PMID 33771173, 2021).
lung carcinoma (7 papers, 2021 to 2024). "LINC01116 overexpressed in lung cancer tissues and cell lines and was significantly associated with proliferation and metastasis." (PMID 38914679, 2024). "In lung cancer, the upregulation of LINC01116 is an important reason for tumor cell proliferation and migration as it enhances the process of epithelial-mesenchymal transition (EMT)." (PMID 34745939, 2021). "It has been reported that LINC01116 is overexpressed in lung cancer and that it could upregulate STAT3 to induce tumor invasion and migration." (PMID 35372012, 2022). "LINC00942, LINC01116, SNHG4, MIR31HG, and LINC00460 had been known to be associated with tumor development and progression and drug resistance in various cancers including lung cancer." (PMID 35083132, 2021). "Recent studies also suggested that LINC01116 played an oncogenic role in lung cancer." (PMID 34408216, 2021).
prostate carcinoma (4 papers, 2017 to 2024). A carcinoma that arises from epithelial cells of the prostate gland. "LINC01116 was first found in prostate cancer, and gene knockdown reduces the integration ability of cancer cells and inhibits carcinogenesis." (PMID 39648148, 2024). "For the detection of LINC01116 function in prostate cancer, we firstly measured the expression of LINC01116 in prostate cancer cells." (PMID 33726770, 2021). "In the present study, we discovered that the location of LINC01116 was most in cytoplasm of prostate cancer cells, indicating that LINC01116 might act as a ceRNA at posttranscriptional level." (PMID 33726770, 2021).
breast cancer (3 papers, 2017 to 2023). A primary or metastatic malignant neoplasm involving the breast. "Additionally, numerous reports have shown that LINC01116 functions as a major regulator of lung cancer (LC), gastric cancer (GC), colorectal cancer (CRC), glioma, osteosarcoma, glioma, head and neck squamous cell carcinoma (HNSC), epithelial ovarian cancer (EOC), and breast cancer (BC)." (PMID 34722518, 2021).
nasopharyngeal carcinoma (3 papers, 2020 to 2021). A carcinoma arising from the nasopharyngeal epithelium. "LINC01116 enhances the transcriptional activity of MYC to accelerate nasopharyngeal carcinoma progression." (PMID 33311496, 2020). "LINC01116 contributes to cell proliferation and migration in nasopharyngeal carcinoma." (PMID 31703161, 2020). "Cytoplasmic LINC01116 interacts with MYC mRNA to stimulate MYC protein and therefore enhance MYC transcriptional activity in nasopharyngeal carcinoma cells." (PMID 31703161, 2020).
non-small cell lung carcinoma (3 papers, 2017 to 2022). A group of at least three distinct histological types of lung cancer, including non-small cell squamous cell carcinoma, adenocarcinoma, and large cell carcinoma. "LINC01116 is a critical component in the advancement of gefitinib-resistant non-small-cell lung carcinoma (NSCLC) by influencing the expression of IFI44, thus offering a novel treatment target for overcoming TKI resistance in NSCLC." (PMID 36567857, 2022). "LINC01116 has previously been found to be involved in two other cancer models: in the progression of glioblastoma; and it is up-regulated in gefitinib resistant non-small cell lung cancer cells." (PMID 34193551, 2021).
endometriosis (2 papers, 2021 to 2025). The growth of functional endometrial tissue in anatomic sites outside the uterine body. "These experiments indicated that LINC01116 plays an important role in promoting cell proliferation and migration in endometriosis." (PMID 33372387, 2021). "We aimed to investigate the function and mechanism of LINC01116 in endometriosis in vitro." (PMID 33372387, 2021).
glioblastoma (2 papers, 2017 to 2021). The most malignant astrocytic tumor (WHO grade IV). "Another lncRNA whose levels significantly increase during differentiation is LINC01116, which has previously been shown to be involved in the progression of glioblastoma (GBM)." (PMID 34193551, 2021).
lung adenocarcinoma (2 papers, 2022 to 2023). A carcinoma that arises from the lung and is characterized by the presence of malignant glandular epithelial cells. "It has been reported that the downregulation of LINC01116 suppresses the AKT signaling pathway in lung adenocarcinoma." (PMID 37321964, 2023). "LINC01116 functions in proliferation, apoptosis, and cell cycle, as an oncogene have been investigated in various cancers, such as glioma, lung adenocarcinoma, prostate cancer, and breast cancer." (PMID 37321964, 2023). "LINC01116 is oncogenic in several other kinds of tumors and promotes lung adenocarcinoma proliferation and metastasis possibly via the Akt pathway." (PMID 36105077, 2022).
diabetes (1 paper, 2024). "For the differentially expressed lncRNAs identified, MIR7-3HG, LINC01116, HIF1A, MEG3, XIST, NEAT1, and HHLA3 have been previously associated with some form of diabetes and diabetes-associated complications." (PMID 38326874, 2024).
epithelial ovarian cancer (1 paper, 2021). "LINC01116 is also upregulated in epithelial ovarian cancer and can inhibit the apoptosis of cancer cell to promote cancer progression." (PMID 33535997, 2021).
testicular germ cell tumor (1 paper, 2021). A germ cell tumor arising from the testis. "However, decreased expression of LINC01116 has been observed in kidney chromophobe (KICH), kidney renal papillary cell carcinoma (KIRP), testicular germ cell tumor (TGCT), and uterine corpus endometrial carcinoma (UCEC)." (PMID 34722518, 2021).
tumor (22 papers, 2017 to 2025). "Thus, LINC01116 plays a key role in tumour progression and may serve as a valuable diagnostic and prognostic marker for lung cancer." (PMID 39648148, 2024). "LINC01116 acts as a competing endogenous RNAs (ceRNA) that binds competitively to microRNAs and plays a critical role in tumour migration and invasion." (PMID 39648148, 2024). "As the expression level of LINC01116 was closely related to the biological behavior of tumor cells, RNA‐seq was used to discover the altered genes after LINC01116 knockdown in Hep‐3B cells." (PMID 38460179, 2024). "LINC01116 is a poor prognostic factor for different types of tumours and plays a role in tumour progression." (PMID 36844873, 2023). "According to the intersection of up-regulated lncRNAs in GSE18842 and GSE19188, seven lncRNAs (LINC00511, LINC01133, DUXAP10, LINC01296, BBOX1-AS1, AFAP1-AS1 and LINC01116) were found to be highly expressed in NSCLC tumor tissues in both datasets." (PMID 33931086, 2021). "Also, relative to normal tissues, the expression of LINC01116 in ER+ and ER– tumor tissues significantly increased and decreased, respectively." (PMID 37321964, 2023). "In addition, we also found that silencing of LINC01116 inhibited the growth of tumors in vivo, eventually resulting in lessened tumor size and lowered tumor weight." (PMID 33311496, 2020). "Taken together, LINC01116 serves a tumor facilitator in NPC." (PMID 31703161, 2020). "Upregulated LINC01116 could promote tumor growth and metastasis in BCa through two pathways." (PMID 33311496, 2020). "Furthermore, immunohistochemistry (IHC) of the excised tumor sections indicated that the expression of Ki67, a proliferation marker, in LINC01116 knockdown group was lower than that in the control group, while overexpression of LINC01116 produced the opposite effects." (PMID 38460179, 2024). "qRT‐PCR results showed that the expression levels of LINC01116, miR‐9‐5p and CCNE1 were significantly higher in LUAD tumour tissues than in the corresponding adjacent tissues, which was consistent with the results of the previous database analysis." (PMID 39648148, 2024). "Several studies have shown the increased expression level of LINC01116 in NSCLC, which promotes the proliferation and invasion of tumour cells; miR‐9‐5p was identified as the significant downstream gene." (PMID 39648148, 2024). "Differential expression analysis showed that LINC01116 and OLFML2B were differentially expressed, with higher expression in tumor tissues (P = 0.045, 0.019)." (PMID 37340445, 2023). "The expressions of Linc01116 and CRNDE were positively correlated with tumor grade and the survival time was significantly different between their high- and low-expression subgroups." (PMID 37547724, 2023). "Gain- (overexpression) and loss-of-function (CRISPRi (Clustered Regularly Interspaced Short Palindromic Repeats interference, RNA interference)) approaches performed in LUAD cancer cell lines did not reveal a clear regulatory role for LINC01116 in tumor cells." (PMID 41367062, 2025). "The data showed significant LINC01116 downregulation in N2 and N3, compared with N1 tissues, and in grades II as well as III, compared to grade I, suggesting the reduction of LINC01116 expression is related to tumor development in ER+ samples." (PMID 37321964, 2023). "Interestingly, the qRT-PCR results indicated that the expression of AC012065.1, LINC01116, TMCC1-AS1 and LINC01060, was significantly higher in tumor tissue while expression of AC002511.2, LINC00426 and ARHGAP31-AS1 was similar between tumor and normal tissue." (PMID 36387100, 2022). "Moreover, differential expression analysis suggested that the levels of LINC01116, LMO7‐AS1, KDM4A‐AS1, KMT2E‐AS1, KTN1‐AS1, LINC00839, DLX6‐AS1, UBL7‐AS1, and DDX11‐AS1 were notably up‐regulated in 77 ESCC samples or 162 EC tumor tissues than in 11 normal tissues." (PMID 36965032, 2023).
cancer (21 papers, 2017 to 2025). A tumor composed of atypical neoplastic, often pleomorphic cells that invade other tissues. "LINC01116 is a long noncoding RNA, and its abnormal expression is associated with a variety of cancers." (PMID 38460179, 2024). "In osteosarcoma, LINC01116 was reported as a potential disease risk factor closely associated with cancer development." (PMID 33499872, 2021). "Given LINC01116’s extensive oncogenic roles in various cancers, its potential role in BCa piques our interest, leading us to further explore LINC01116’s involvement in BCa and deepen our understanding of its functional relevance in this setting." (PMID 38255219, 2024). "They showed that LINC01116 acts as a cancer-promoting oncogene via epithelial-mesenchymal transition." (PMID 37340445, 2023). "LINC01116, for instance, has a well-established role in cancer development, with numerous studies supporting its involvement in promoting cell proliferation, invasion, migration, and apoptosis." (PMID 37834450, 2023). "Previously, it has been revealed that lncRNA LINC01116 is abnormally up-regulated in several types of cancer." (PMID 33499872, 2021). "LINC01116 plays oncogenic roles in multiple cancer types, while only one previous study reported its involvement in CRC." (PMID 33499872, 2021). "Such broad oncogenic function of LINC01116 in different cancer types aroused our interest in its role in BCa." (PMID 33311496, 2020). "LINC01116 was overexpressed in several cancers, and was transcriptionally repressed after Sulforaphane (SFN) treatment." (PMID 29383105, 2017). "The expression of LINC01116 is significantly upregulated in all these cancers." (PMID 37321964, 2023). "At present, the functions of LINC01116 in other cancers have been discussed in various researches, while its function in LAD remains unclear." (PMID 34090440, 2021). "The functions of LINC01116 have been characterized in several types of cancer." (PMID 33535997, 2021). "Accumulating reports have indicated that LINC01116 plays a vital part in many cancers." (PMID 33311496, 2020). "Among these DEirlncRNAs included in the model, some have been revealed to be related to the development of cancers, such as LINC00958, FOXF1 adjacent non-coding developmental regulatory RNA (FENDRR), LINC01116, and LINC00941." (PMID 34408216, 2021).
LINC01116 also shares sentences with these, for which no sentence is quoted: gastric cancer (4 papers); anaplastic astrocytoma (1); astrocytomas (1); colorectal cancer (1); head and neck squamous cell carcinoma (1); liver cancer (1); oligodendroglioma (1); oral squamous cell carcinoma (1); prostate adenocarcinoma (1); small cell lung carcinoma (1); triple-negative breast carcinoma (1).